CTTN (cortactin)
Diseases named in the same sentence as CTTN in open-access papers (continued):
Sharing a sentence is not in itself a finding about the gene and the disease.
breast carcinoma (continued). "CRP2-GFP accumulated in actin- and cortactin-enriched areas located at the cell leading edge, in extending pseudopodia, supporting the idea that CRP2 contributes to the mesenchymal mode of invasion in breast cancer cells." (PMID 26883198, 2016). "Critically, PBF induces potent cellular invasion and migration in thyroid and breast cancer cells, which is entirely abrogated in the absence of CTTN." (PMID 27603901, 2016). "Although CTTN expression has previously been investigated in breast cancer, it has not been addressed in differentiated thyroid cancer (DTC)." (PMID 27603901, 2016). "The present studies report for the first time a role of Fe65 in suppressing breast cancer migration and invasion by showing that Fe65 binds to cortactin in ERα negative breast cancer cells and promotes its acetylation through the Tip60 acetyltransferase." (PMID 26166158, 2015). "The present studies have extended the function of Fe65 to ERα negative breast cancers by showing for the first time that it suppresses cell migration and invasion by recruiting Tip60 to cortactin and stimulating its acetylation." (PMID 26166158, 2015). "The present study is the first to show that Fe65 binds to cortactin and increases its acetylation to suppress breast cancer migration and invasion, possibly through its negative effect on invadopodia formation." (PMID 26166158, 2015). "Taken together, we conclude that the development of malignant breast tumors in either WT or MMTV-cyclin D1 mice was not increased due to overexpression of human cortactin." (PMID 16536875, 2006). "Human breast cancer studies have demonstrated that the LH–LHR signaling axis promotes tumor cell adhesion, migration, and stromal invasion by activating cortactin/N-WASP phosphorylation cascades, and the observed LHR upregulation in canine models may suggest analogous pro-metastatic mechanisms." (PMID 40431589, 2025). "However, the role of cortactin expression in breast cancer prognosis has not been sufficiently elucidated." (PMID 37761244, 2023). "Multiple observations have evidenced that cortactin expression is increased in various types of human cancers, including gastric cancer, colorectal carcinoma, pancreatic cancer, head and neck squamous carcinomas (HNSCC), hepatocellular cancer, breast cancer and ovarian cancers." (PMID 31936446, 2020). "Interestingly, cortactin phosphorylated at Y-421 and Y-466, but not at Y-482, was previously shown to recruit Vav2 and Rac3, promoting invadopodial maturation in invasive breast cancer cells." (PMID 31936446, 2020). "Although cortactin is overexpressed in many types of cancers such as head and neck squamous carcinoma, oral squamous carcinoma, breast cancer or melanoma, we could not find any regulation in protein levels in human colon cancer tissues." (PMID 29472634, 2018). "As observed in breast cancer cells, knockdown of liprin-α1 did not prevent formation of focal adhesions or cortactin-positive structures in metastatic or primary persistent HNSCC cell lines, although focal adhesions were smaller or more elongated than in control cells." (PMID 27075696, 2016). "In addition, overexpression of cortactin in MDA-MB-231 breast cancer cells did not affect the growth rate, but promoted the formation of bone metastases." (PMID 16536875, 2006). "Additionally, we found that four of these sEV surface proteins (CTTN, FSCN1, ICAM1, MMP14) were exclusively present in sEVs from high invadopodia activity cells, which have previously been reported in sEVs that are preferentially secreted from invadopodia in breast cancer cells." (PMID 37014551, 2023). "In survival analysis, patients with high cortactin expression showed poorer OS and DFS than those with low cortactin expression in all patients with breast cancer and non-TNBC patients." (PMID 37761244, 2023).
breast carcinoma (continued). "Similarly it has been described for different breast cancer cell lines, that the expression level of cortactin does not directly correlate with the ability of cells to form invadopodia and to migrate, stressing the importance of the subcellular localisation of cortactin." (PMID 27911942, 2016).
melanoma (36 papers, 2010 to 2025). A malignant, usually aggressive tumor composed of atypical, neoplastic melanocytes. "Overexpression of cortactin is linked to invasive cancers, including melanoma, colorectal cancer, and glioblastoma, making it an important biomarker for invasive cancers." (PMID 30949052, 2019). "Notwithstanding this, CTTN overexpression has been extensively linked to invasive cancers, including melanoma, colorectal cancer, and glioblastoma." (PMID 27603901, 2016). "A role of invadopodia in the extravasation of carcinoma across lung endothelial cell layers or human melanoma across rat brain endothelial cells has been shown previously by targeting the invadopodia drivers cortactin, seprase, Tks4 or Tks5." (PMID 37894438, 2023). "Cortactin can promote cell migration, cell mortality, and tumor invasiveness in melanoma, colorectal cancer, and glioblastoma, and its expression was demonstrated to be significantly associated with poorer survival rates in patients with OSCC." (PMID 36980391, 2023). "Correspondingly, a study of invasive and metastatic melanomas showed cortactin expression with a high density of (very strong) expression in SCC of 83%." (PMID 36980391, 2023). "This was also seen in cultured melanoma cells, in which cortactin was distributed in the membrane ruffles and lamellipodia." (PMID 36980391, 2023). "Controls included the use of short interference RNA and catalytically-dead mutant that prevented the dephosphorylation of cortactin and hence the decrease the extracellular matrix degradation by melanoma cells." (PMID 34088320, 2021). "Melanoma cells also exhibit abnormal localization of ABP cortactin, which corresponds to the colocalization of filamentous actin in the cultured melanoma cell cortex." (PMID 34194957, 2021). "This implies a potential role of cortactin in the regulation of melanoma progression and provides a reasonable basis for targeted intervention in melanoma treatment." (PMID 34194957, 2021). "Short interference RNA and a catalytically-dead mutant of Shp1 expressed in A375MM melanoma cells were used to evaluate the role of the specific Shp1-mediated dephosphorylation of cortactin." (PMID 34088320, 2021). "The data show that Shp1 was recruited to invadopodia and promoted the dephosphorylation of cortactin at tyrosine 421, leading to an attenuated capacity of melanoma cancer cells to degrade the extracellular matrix." (PMID 34088320, 2021). "It was also found that among the 170 melanocyte lesions (including 106 cutaneous malignant melanoma (MM), 24 dysplastic nevi (DN), and 40 common melanocytic nevi (CMN)) collected, cortactin is strongly positively expressed in all three types of melanoma." (PMID 34194957, 2021). "Co-localization of F-actin with invadopodium structural component Cortactin in MCR:SATB2 melanoma cell lines confirmed these foci to be invadopodia." (PMID 33527896, 2021). "To further explore the relationships between RNF128, CD44, and CTTN, we detected their expression in 30 pairs of melanoma and matched peritumoral tissues." (PMID 30832692, 2019). "Fyn has also been shown to co-localize with cortactin in the mediation of metastatic murine melanoma cell migration." (PMID 27363897, 2016). "The second panel tested was composed of 6 melanoma-derived cell lines; CTTN showed the highest knockdown out of all the targets tested." (PMID 24987961, 2014). "For instance, all peptides that originate from VIM or CTTN are consistently more abundant in melanoma cells while peptides from LCP1 and ARHGDIB are consistently more abundant in monocytes, although the magnitudes are influenced by the baseline peptide intensity." (PMID 40775377, 2025). "Notably, proteins associated with cell adhesion and mobility, such as VIM, CTTN, and LGALS3, are more abundant in melanoma cells." (PMID 40775377, 2025). "Cortactin promotes EMT in melanoma, gastric cancer, and oral squamous cell carcinoma." (PMID 38985526, 2024).
melanoma (continued). "Interestingly, in melanoma patients, high levels of cortactin expression are correlated with poor disease-specific survival; this is possibly because cortactin phosphorylation is a key step during invadopodia maturation and migration." (PMID 36978819, 2023). "As invadopodia initially form precursors enriched in F-actin, Arp2/3 and cortactin which then mature to acquire proteolytic activity, we suggest that in situ melanoma cells assemble invadopodia precursor and that the maturation step occurs during melanoma progression." (PMID 36899008, 2023). "First, NAC1 contributes to cortactin deacetylation and augments the migration of melanoma cells." (PMID 37626718, 2023). "Altogheter, these in vivo data support the finding that the GroPIns-Shp1-cortactin complex by inhibiting invadopodia formation, may affect the invasiveness of melanoma cells in an in vivo model system." (PMID 34088320, 2021). "Therefore, cortactin regulates migration in G361 melanoma cells which in turn is dependent on its phosphorylation status." (PMID 27339664, 2016). "Using immunochemistry on human tissue, it has been shown that there is significantly higher cortactin (a multidomain actin-binding protein important for the function of cytoskeleton) expression in melanomas than in nevi and higher expression in metastatic melanoma than in invasive primary melanomas." (PMID 20936153, 2010). "Cortactin is overexpressed in many cancers at high risk of invasiveness and metastasis, including hepatocellular carcinoma, colorectal cancer, glioblastoma, HNSCC, oral squamous cell carcinoma, lung squamous cell carcinoma, gliosarcoma, breast cancer, and melanoma." (PMID 36980391, 2023). "The main finding here reported is that cortactin is a specific substrate of the tyrosine phosphatase Shp1 and that its phosphorylation/dephosphorylation affects invadopodia formation and, as a consequence, the ability of melanoma cells to invade the extracellular matrix." (PMID 34088320, 2021). "Downregulated RNF128 activates Wnt signaling to induce cellular EMT and stemness by ubiquitinating and degrading CD44/CTTN, and RNF128 is a reliable diagnostic and prognostic biomarker, and a deeper understanding of RNF128 may contribute to the treatment of melanoma." (PMID 30832692, 2019). "When comparing monocytes to melanoma cells, proteins such as VIM, LMNA, CALU, LGALS3, CTTN, and CORO1A are strongly and confidently differentially expressed." (PMID 40775377, 2025). "The acetylation status of CTTN, modulated by the NACC1–HDAC6 deacetylation system, induces the acceleration of melanoma cell migration activity via an actin-dependent cellular process." (PMID 39769395, 2024). "A previous study showed that downregulation of RNF128 induced EMT and stemness in melanoma cells through CD44 and CTTN ubiquitination." (PMID 37383713, 2023). "In melanoma, low expression of RNF128 activates Wnt/β-catenin signaling to induce cellular EMT and stemness and protects CD44 and cortactin from degradation mediated by ubiquitination." (PMID 36644633, 2022). "The downregulation of RNF128 promoted melanoma cell proliferation in vitro and in vivo, through the degradative ubiquitination of CD44 and cortactin (CTTN)." (PMID 33800394, 2021). "The expression of cortactin and vinculin was also analyzed by western immunoblotting in the Mock- or Snail-transfected B16F1 melanoma cells." (PMID 33917849, 2021). "The downregulation of RNF128 promotes the progression of melanoma by ubiquitination and degradation of CD44/cortactin to activate Wnt signaling, thereby inducing cellular EMT and obtaining stem cells." (PMID 33195233, 2020). "In melanoma, RNF128 interferes with the ubiquitination and degradation of CD44 and cortactin proteins, activates the Wnt pathway, and promotes the cellular EMT and stem cell development." (PMID 33195233, 2020).
melanoma (continued). "Low levels of RNF128 were shown to induce melanoma cell EMT and promote lung metastasis through the Wnt/β-catenin pathway via the ubiquitination of CD44 and CTTN." (PMID 30832692, 2019). "Additionally, the activation of the Wnt signaling pathway in melanoma is known to occur through the ubiquitination and degradation of CD44 and cortactin by RNF128, subsequently inducing EMT and stemness in melanoma cells." (PMID 38886806, 2024). "Having shown that GroPIns is able to modulate the Shp1-dependent inhibition of A375MM melanoma cell ECM degradation, we tested whether this modulation could involve Shp1 activity on cortactin." (PMID 34088320, 2021). "Next, to investigate whether the inhibition of FAK–paxillin interactions affects melanoma invasion, siFAK-treated A375 melanoma cells expressing wild-type FAK-GFP or FAK-I936/I998-GFP were plated on Cy3-gelatin and labeled for actin and cortactin." (PMID 33919725, 2021). "Melanocytes do not produce invadopodia and not all melanoma derived cells lines are able to produce invadopodia; validated by the co-localisation of cortactin with F-actin staining and gelatin degradation which defines completion of the invadopodia lifecycle." (PMID 27765920, 2016). "Surprising, invadopodia, identified as actin- and cortactin-rich punctate structures, were present in all melanoma cell lines, including in situ melanoma with no apparent link between the number of invadopodia per cell and their respective invasive potential in the collagen matrix." (PMID 33919725, 2021). "But there is no statistical difference in cortactin immunostaining intensity among CMN, DN, and MM, indicating that the protein is highly expressed in different types of melanomas." (PMID 34194957, 2021). "The near-absence of F-actin/cortactin-positive clusters, GTP-Cdc42/Rac-containing adhesions, and matrix degradation in p85β-depleted melanoma cells, supports the idea that p85β localization might be a primary event in invadopodium formation in melanoma." (PMID 25217619, 2014).
colorectal cancer (24 papers, 2008 to 2024). A primary or metastatic malignant neoplasm that affects the colon or rectum. "PTBP1 expression has previously been associated with invasiveness in colorectal cancer through alternative splicing of cortactin." (PMID 39010058, 2024). "CTTN expression has been associated with tumor aggressiveness in leukemia, colorectal cancer, esophageal cancer, and hepatoma among others." (PMID 29872504, 2018). "The gene CTTN has been reported overexpressed in various cancers, including colorectal cancer, and had the function of promoting tumor cell migration." (PMID 36523772, 2022). "Several studies show that Cortactin plays a role in cell migration and invasion in colorectal cancer, gastric cancer, lung cancer and pancreatic cancer." (PMID 32369440, 2020). "CTTN and SRC have been implicated in cell proliferation, motility, and invasion in various types of cancer, such as esophageal cancer, colorectal cancer, laryngeal carcinoma, and lung cancer." (PMID 31815134, 2019). "Cortactin is a potential molecular driver in several cancers, including lung, brain, and colorectal cancer." (PMID 29986736, 2018). "Recently, in colorectal cancer (CRC) Cortactin overexpression inhibited the ubiquitin-mediated degradation of EFGR by suppressing the coupling of c-Cbl with EGFR." (PMID 30181811, 2018). "Recently, in colorectal cancer (CRC) Cortactin overexpression has been correlated with inhibition of ubiquitin-mediated degradation of EFGR by suppressing the coupling of c-Cbl with EGFR." (PMID 30181811, 2018). "Knocking down cortactin isoform-a significantly decreased cell migration and invasion in colorectal cancer cells." (PMID 28404950, 2017). "To explore the relation between PTBP1 and cortactin isoform-a, we first detected their mRNA expression levels in colorectal cancer tissues." (PMID 28404950, 2017). "Cortactin (CTTN) is overexpressed in various tumors, including head and neck squamous cell carcinoma and colorectal cancer (CRC), and can serve as a biomarker of cancer metastasis." (PMID 27903975, 2017). "Our previous study also found that CTTN is overexpressed in colorectal cancer, and correlated with metastasis of colorectal cancer." (PMID 27903975, 2017). "We made a CTTN expression assay in seven colorectal cancer cell lines using qRT-PCR and western blot." (PMID 27903975, 2017). "Then after siRNA-mediated knockdown of PTBP1, cortactin isoform-a was significantly decreased in three colorectal cancer cell lines by real-time PCR and RT-PCR but the total mRNA levels of cortactin remained slightly unchanged." (PMID 28404950, 2017). "Compared with normal tissues, primary cancerous colorectal tissues showed assembly of cortactin in lymph nodes, suggesting a close involvement of cortactin in metastasis of colorectal cancer cells." (PMID 26134506, 2015). "Notably, interaction of cortactin and ZO-1 was proposed to play a role in colorectal cancer progression." (PMID 38646547, 2024). "In addition, applying HEART on two subpopulations of megakaryocytes, we found several potential cancer biomarkers (CTTN, S100A4, S100A6, UBA52, FAU, and VIM, etc.)associated with colorectal cancer progression and metastasis in literature." (PMID 36523772, 2022). "Furthermore, we applied HEART to a single-cell dataset of a colorectal cancer patient and identified several potentially metastasis-related biomarkers, CTTN, S100A4, S100A6, etc." (PMID 36523772, 2022). "The Src substrate CTTN has been found to be overexpressed in various cancers, including human colorectal cancer, esophageal tumors, and non-small-cell lung cancer, and HCC and CTTN overexpression closely correlates with tumor aggressiveness, cell adhesion, and cell motility." (PMID 31138777, 2019). "Also the mRNA levels of PTBP1 and cortactin isoform-a were cooperatively expressed in colorectal cancer tissues." (PMID 28404950, 2017). "Our study found CTTN could promote the proliferation and enhance clonogenic ability of colorectal cancer cells." (PMID 27903975, 2017).
colorectal cancer (continued). "Given that PTBP1 may regulate cortactin exon 11 which can be seen in RT-PCR, we performed RNA immunoprecipitation and showed that PTBP1 efficiently coprecipitated cortactin RNA in the colorectal cancer cell line HCT-116, confirming a direct interaction." (PMID 28404950, 2017). "Influences on cell motility caused by PTBP1 maybe due to the splicing events of exon 11 of cortactin gene in colorectal cancer." (PMID 28404950, 2017). "Previously, overexpression of cortactin was revealed in a few types of colorectal cancers." (PMID 26134506, 2015). "Accordingly, one study reported interaction of Cortactin and zonula occludens-1 (ZO-1) in migrating or polarized colorectal carcinoma cells, and we previously showed localization of the protein to sites of matrix degradation in a gelatin-based extracellular matrix degradation assay in vitro." (PMID 26345720, 2015). "In our study, western blot and immunohistochemical analysis showed that pTy421-cortactin was overexpressed in nearly 70% of the tumors examined, suggesting that pTy421-cortactin levels could be a potential biomarker for colorectal cancer." (PMID 24465712, 2014). "The AceView program predicts numerous putative isoforms for cortactin, but the splice-variants occurring in colonic epithelium or colorectal cancers have not yet been reported." (PMID 18844995, 2008). "Consequently, we supposed that a series of genes, CTTN, S100A4, S100A6, etc., were potential colorectal cancer metastasis biomarkers." (PMID 36523772, 2022). "In the present study, we demonstrate that pTyr421 cortactin is overexpressed in colorectal cancer without concomitant changes in mRNA levels." (PMID 24465712, 2014).